ZNF620 (zinc finger protein 620)
Description:
May be involved in transcriptional regulation.
Synonyms: MGC50836
Tractability: PROTAC: ubiquitination databases record sites on it.
Gene: Protein-coding gene on chromosome 3 (40,477,131 to 40,518,736, forward strand). Ensembl gene ENSG00000177842.
Subcellular location: Nucleus
Subcellular location (Human Protein Atlas): Centrosome
Pathways (Reactome):
Gene expression (Transcription): Generic Transcription Pathway
Gene Ontology:
Molecular function: protein binding; DNA-binding transcription factor activity, RNA polymerase II-specific; RNA polymerase II transcription regulatory region sequence-specific DNA binding
Biological process: regulation of transcription by RNA polymerase II; regulation of DNA-templated transcription
Cellular component: nucleus
Genetic constraint (gnomAD): Loss-of-function variants: 9 observed, 13.47 expected, observed/expected ratio (o/e) 0.67, 90% interval 0.4 to 1.17. The upper end of that interval is the gene's LOEUF score, 1.17, which puts it in group 5 of 6, group 1 being the genes least tolerant of losing a copy. Missense variants: 461 observed, 528.52 expected, observed/expected ratio (o/e) 0.87, 90% interval 0.81 to 0.94. Synonymous variants: 166 observed, 188.58 expected, observed/expected ratio (o/e) 0.88, 90% interval 0.77 to 1.
Homologues: Orthologues: chimpanzee ZNF620 (99% identical), macaque ZNF620 (96% identical), Drosophila melanogaster CG3281 (25% identical), Drosophila melanogaster Phs (24% identical), Drosophila melanogaster CG2712 (23% identical). Paralogues in human: ZNF619 (60% identical), ZNF566 (41% identical), ZNF582 (40% identical), ZNF805 (39% identical), ZNF266 (39% identical), ZNF599 (39% identical), ZFP37 (38% identical), ZFP69B (38% identical), ZNF25 (38% identical), ZNF264 (38% identical), ZNF555 (38% identical), ZNF77 (37% identical), and 50 more.
Diseases named in the same sentence as ZNF620 in open-access papers:
ZNF620 is named in the same sentence as 1 disease in open-access papers, as found by Europe PMC text mining. Sharing a sentence is not in itself a finding about the gene and the disease.
ZNF620 shares sentences with these, for which no sentence is quoted: cancer (1 paper).